POLR3G (RNA polymerase III subunit G)
Description:
DNA-dependent RNA polymerase catalyzes the transcription of DNA into RNA using the four ribonucleoside triphosphates as substrates. Specific peripheric component of RNA polymerase III (Pol III) which synthesizes small non-coding RNAs including 5S rRNA, snRNAs, tRNAs and miRNAs from at least 500 distinct genomic loci. Acts as a long tether that bridges POLR3C/RPC3-POLR3F/RPC6-POLR3G/RPC7 heterotrimer and the mobile stalk of Pol III, coordinating the dynamics of Pol III stalk and clamp modules during the transition from apo to elongation state. Pol III exists as two alternative complexes defined by the mutually exclusive incorporation of subunit POLR3G/RPC7alpha or POLR3GL/RPC7beta. POLR3G/RPC7alpha modulates Pol III transcriptome by specifically enhancing the transcription of snaR-A non-coding RNAs. At resting state, occupies the active site of apo Pol III and keeps Pol III in an autoinhibitory mode, preventing non-specific transcription. Pol III plays a key role in sensing and limiting infection by intracellular bacteria and DNA viruses. Acts as a nuclear and cytosolic DNA sensor involved in innate immune response. Can sense non-self dsDNA that serves as template for transcription into dsRNA. The non-self RNA polymerase III transcripts, such as Epstein-Barr virus-encoded RNAs (EBERs), induce type I interferon and NF-kappa-B through the RIG-I pathway.
Synonyms: RPC32; RPC7; C31
Tractability: Small molecule: a structure with a bound ligand is known. PROTAC: ubiquitination databases record sites on it.
Safety:
Unwanted effects reported when the protein is acted on. In parentheses: how it was acted on, where the effect was seen, and who reports it.
rash (source: ClinPGx)
Gene: Protein-coding gene on chromosome 5 (90,471,748 to 90,514,559, forward strand). Ensembl gene ENSG00000113356.
Subcellular location: Nucleus; Cytoplasm
Subcellular location (Human Protein Atlas): Nucleoplasm; Cytosol; Nuclear bodies
Pathways (Reactome):
Gene expression (Transcription): RNA Polymerase III Abortive And Retractive Initiation; RNA Polymerase III Chain Elongation; RNA Polymerase III Transcription Initiation From Type 1 Promoter; RNA Polymerase III Transcription Initiation From Type 2 Promoter; RNA Polymerase III Transcription Initiation From Type 3 Promoter; RNA Polymerase III Transcription Termination
Immune System: Cytosolic sensors of pathogen-associated DNA
Gene Ontology:
Molecular function: chromatin binding; protein binding; DNA-directed RNA polymerase activity
Biological process: cell population proliferation; positive regulation of innate immune response; positive regulation of interferon-beta production; termination of RNA polymerase III transcription; transcription by RNA polymerase III; transcription initiation at RNA polymerase III promoter; regulation of transcription by RNA polymerase III
Cellular component: nuclear body; nucleoplasm; nucleus; RNA polymerase III complex; cytoplasm; cytosol
Genetic constraint (gnomAD): Loss-of-function variants: 21 observed, 25.74 expected, observed/expected ratio (o/e) 0.82, 90% interval 0.58 to 1.17. The upper end of that interval is the gene's LOEUF score, 1.17, which puts it in group 5 of 6, group 1 being the genes least tolerant of losing a copy. Missense variants: 201 observed, 222.26 expected, observed/expected ratio (o/e) 0.9, 90% interval 0.81 to 1.02. Synonymous variants: 62 observed, 65.15 expected, observed/expected ratio (o/e) 0.95, 90% interval 0.77 to 1.18.
Homologues: Orthologues: chimpanzee POLR3G (99% identical), macaque POLR3G (98% identical).
Diseases named in the same sentence as POLR3G in open-access papers:
POLR3G is named in the same sentence as 30 diseases in open-access papers, as found by Europe PMC text mining. Sharing a sentence is not in itself a finding about the gene and the disease. The quoted sentences say what the papers report.
prostate carcinoma (9 papers, 2019 to 2024). A carcinoma that arises from epithelial cells of the prostate gland. "The cell-permeable small molecule ML-60218 inhibits pol III and causes differentiation, POLR3G depletion, and significant reductions in the proliferation, invasiveness, tumour-initiating activity and viability of prostate cancer cells." (PMID 30820548, 2019). "Several studies have identified overexpression of POLR3G in various cancers, including prostate cancer and breast cancer." (PMID 39039528, 2024). "According to existing reports, the inhibition of POLR3G has demonstrated a specific halt in proliferation and induction of cell death in prostate cancer cells." (PMID 38240703, 2024). "The inhibition of Pol III activity by depleting POLR3G in prostate cancer cells suppresses cancer stem cell proliferation and initiates cell differentiation." (PMID 36656267, 2023). "POLR3G is selectively upregulated in prostate cancer, for example, in contrast to POLR3GL and the large Pol III subunit POLR3A, which remain unchanged compared to matched normal cells." (PMID 36710885, 2022). "ML-60218 is otherwise effective at inhibiting Pol III transcription in contexts with high POLR3G expression, including breast and prostate cancer cell lines." (PMID 36710885, 2022). "In PC-3 prostate cancer cells, POLR3G is directly regulated by NANOG, and reciprocally influences the levels of NANOG through the expression of DR2 Alu elements." (PMID 36710885, 2022). "In support and extension of this finding, it was shown that POLR3G inhibition resulted in prostate cancer cell-specific proliferation arrest and cell death and that POLR3G overexpression correlated with bad prognosis of transitional cell carcinoma." (PMID 36497214, 2022). "Similar results were observed at the cellular level; POLR3G expression was elevated in the prostate cancer cell line PC-3 compared to the immortalized healthy prostate epithelium cell line PNT2C2." (PMID 33194434, 2020). "In summary, this study demonstrates that the inhibitory effect of POLR3G on cell differentiation, first discovered in hESC, is also a feature of prostate cancer cells." (PMID 30820548, 2019). "CDC27 is a tumor suppressor, its downregulation inhibits the proliferation of cancer cells, POLR3G is required for proliferation, its depletion triggers proliferative arrest and differentiation of prostate cancer cells." (PMID 31540229, 2019). "We found that prostate cancer cells also differentiate when depleted of POLR3G, either by RNAi or by treatment with ML-60218." (PMID 30820548, 2019). "We find that depleting POLR3G can indeed promote differentiation and suppress proliferation and viability of prostate cancer cells." (PMID 30820548, 2019). "Because of the unmet clinical need for effective strategies to combat androgen-independent prostate cancer, we explored the influence of POLR3G in a model that is refractory to standard treatment." (PMID 30820548, 2019). "Nevertheless, NANOG regulates POLR3G expression in prostate cancer cells, indicating that POLR3G mRNA levels may be driven by multiple transcription factors and regulatory programs." (PMID 37894362, 2023). "Depletion of POLR3G selectively triggers proliferative arrest and differentiation of prostate cancer cells, responses not elicited when POLR3GL is depleted." (PMID 30820548, 2019).
bladder cancer (7 papers, 2020 to 2025). "Through RNA sequencing and bioinformatics analysis of POLR3G knockdown cells, we identified potential molecular mechanisms underlying its role in bladder cancer, which were further validated by molecular experiments." (PMID 39039528, 2024). "This study provides a foundation for future investigations into the molecular mechanisms underlying bladder cancer and highlights the importance of POLR3G in its pathogenesis." (PMID 39039528, 2024). "In previous study, we found POLR3G was up-regulated in bladder cancer, and high POLR3G expression was associated with higher tumor stage, tumor grade and other adverse clinicopathologic features." (PMID 39039528, 2024). "KM survival analysis showed that POLR3G expression was negatively associated with progression-free survival and disease specific survival as well as overall survival in bladder cancer patients." (PMID 39039528, 2024). "In our previous study, we found POLR3G was up-regulated in bladder cancer, and higher expression of POLR3G was associated with more advanced tumor stage and poorer prognosis." (PMID 39039528, 2024). "A significant upregulation of polymerase (RNA) III (DNA directed) polypeptide G (POLR3G)Glutathione peroxidase 2 was identified in advanced bladder cancer tissues, correlating with aggressive tumor behavior and reduced survival." (PMID 40740483, 2025). "This potential immunomodulatory role of POLR3G opens new avenues for research into immune-based therapies for bladder cancer, particularly those targeting the Wnt signaling pathway." (PMID 39039528, 2024). "More specifically, the expression of POLR3G was significantly correlated with the infiltrating levels of immune cells and the expression of immune checkpoint molecules in bladder cancer." (PMID 39039528, 2024). "To investigate the molecular function of POLR3G in bladder cancer cells, we knocked down POLR3G in T24 and BIU87 cells." (PMID 39039528, 2024). "The knockdown of POLR3G significantly inhibited the proliferation, migration, and invasion capabilities of bladder cancer cells, highlighting its importance in tumor aggressiveness." (PMID 39039528, 2024). "To investigate the functional role of POLR3G, we performed functional experiments in bladder cancer cell lines." (PMID 39039528, 2024). "In this study, we aim to evaluate the dynamic expression of POLR3G during the development of bladder cancer in animal models and the potential role of POLR3G to serve as a novel therapeutic target." (PMID 39039528, 2024). "Future studies should focus on the detailed mechanisms by which POLR3G regulates these signaling pathways and its potential as a biomarker for early detection and prognosis of bladder cancer." (PMID 39039528, 2024). "We observed a progressive upregulation of POLR3G expression during the bladder cancer development and progression." (PMID 39039528, 2024). "We further conducted RNA sequencing on POLR3G-knockdown bladder cancer cells, and Metascape was employed to perform the functional enrichment analysis of the differentially expressed genes (DEGs)." (PMID 39039528, 2024). "This study aims to evaluate the role of POLR3G in the development and progression of bladder cancer and the potential of POLR3G to serve as a novel therapeutic target." (PMID 39039528, 2024). "In this study, we established a rat model of bladder cancer induced by N-butyl-N-(4-hydroxybutyl) nitrosamine (BBN) to investigate the dynamic changes in POLR3G protein expression during bladder cancer initiation and progression." (PMID 39039528, 2024). "The consistent upregulation of 117 genes and downregulation of 73 genes across both T24 and BIU87 cell lines suggested a robust and conserved regulatory role of POLR3G in bladder cancer." (PMID 39039528, 2024). "Future studies should aim to validate these findings in human clinical samples and explore the interplay between POLR3G and other oncogenic pathways to provide a more comprehensive understanding of bladder cancer biology." (PMID 39039528, 2024).
bladder cancer (continued). "We examined the dynamic change of POLR3G expression during the development of BBN-induced bladder cancer." (PMID 39039528, 2024). "In conclusion, our study elucidates the dynamic expression of POLR3G during bladder cancer progression and its significant role in modulating bladder cancer cell proliferation, migration, and invasion." (PMID 39039528, 2024). "To investigate the role of POLR3G in bladder cancer cells, we conducted RNA sequencing on POLR3G-knockdown and control bladder cancer cells." (PMID 39039528, 2024). "The upregulation of POLR3G observed in our BBN-induced rat model of bladder cancer suggests that POLR3G plays a crucial role in the carcinogenesis and progression of bladder cancer." (PMID 39039528, 2024). "The expression of POLR3G in bladder cancer cell line T24 and human uroepithelial cell line SV-HUC-1 were detected via quantitative real time polymerase chain reaction (qRT-PCR)." (PMID 33194434, 2020). "Our findings suggest that POLR3G plays a crucial role in bladder cancer progression and could serve as a potential therapeutic target." (PMID 39039528, 2024). "The positive correlation between POLR3G expression and the histopathological malignancy grade indicates that POLR3G could serve as a potential biomarker for bladder cancer progression." (PMID 39039528, 2024). "Our functional experiments further elucidated the role of POLR3G in bladder cancer cell behavior." (PMID 39039528, 2024). "Furthermore, we aimed to elucidate the impact of POLR3G on bladder cancer cell migration and invasion using Transwell migration and invasion assays." (PMID 39039528, 2024). "Collectively, these in vitro results strongly suggest that targeting POLR3G might suppress the malignant phenotype of bladder cancer cells." (PMID 39039528, 2024). "Given the known roles of the Wnt pathway in immune cell regulation and tumor immune evasion, our findings imply that POLR3G could influence the tumor microenvironment and immune surveillance in bladder cancer." (PMID 39039528, 2024). "Additionally, we performed in vitro functional assays to explore the impact of POLR3G on bladder cancer cell behavior." (PMID 39039528, 2024). "Our previous study found POLR3G may have significant implications for immune mechanisms in bladder cancer." (PMID 39039528, 2024). "However, the upstream regulatory mechanisms of POLR3G expression and its interactions with other signaling pathways in bladder cancer remain unclear and warrant further investigation." (PMID 40740483, 2025). "Furthermore, evidence has shown that POLR3G promoted the EMT process in bladder cancer." (PMID 40717692, 2025). "The downregulation of Wnt pathway-related proteins such as Wnt5a/b, DVL2, LRP-6, and phosphorylated LRP-6 upon POLR3G knockdown was further confirmed by Western blotting, indicating that POLR3G might influence bladder cancer behavior through the Wnt signaling pathway." (PMID 39039528, 2024). "Thus, POLR3G might play an important role in promoting the development and progression of bladder cancer, and may serve as a novel therapeutic target." (PMID 39039528, 2024). "Furthermore, the study primarily focuses on the role of POLR3G, and while the results are compelling, other molecular players and pathways involved in bladder cancer progression may have been overlooked." (PMID 39039528, 2024). "The downregulation of Wnt pathway-related proteins such as Wnt5a/b, DVL2, LRP-6, and phosphorylated LRP-6 upon POLR3G knockdown was further confirmed by Western blotting, indicating that POLR3G may affect bladder cancer behavior through the Wnt signaling pathway." (PMID 39039528, 2024). "Research has shown that the RNA polymerase III subunit G (POLR3G) can activate the PI3K/Akt signaling pathway, promoting EMT in bladder cancer, and enhancing the migration and invasion of bladder cancer cells both in vitro and in vivo." (PMID 40635786, 2025).
bladder cancer (continued). "Functional assays further demonstrated that the prometastatic effects of POLR3G were mediated through this pathway, both in vitro and in vivo, establishing POLR3G as a critical effector of EMT and metastasis in bladder cancer." (PMID 40740483, 2025). "Results showed that POLR3G was lowly expressed in the normal urothelium of rats, while its expression was significantly up-regulated during the development of BBN-induced bladder cancer." (PMID 39039528, 2024). "In addition, POLR3G promotes cell migration and EMT in bladder cancer." (PMID 40717692, 2025). "The specific role of POLR3G in the context of cGAS-STING activation and bladder cancer is not well-established, and further research is needed to elucidate its significance." (PMID 38240703, 2024).
breast carcinoma (6 papers, 2020 to 2024). "In contrast, the highest expression of the POLR3G gene was detected in basal subtypes of breast cancer." (PMID 36497214, 2022). "When analyzing the transcriptomic data of clinical cases demonstrating POLR3G overexpression in basal breast cancer, we determined the genes being positively or negatively correlated to POLR3G expression in breast cancer patients." (PMID 36497214, 2022). "Our data show that the expression of POLR3G in breast cancer samples was negatively correlated with that of eight out of ten genes (GATA3; XBP1; AGR2; SIDT1; AR; SPDEF; FOXA1; MLPH) in a list of signature genes most differentially expressed in luminal A compared to basal-like tumors." (PMID 36497214, 2022). "Interestingly though, POLR3G itself was included into a signature of classifier genes expressed in basal B breast cancer cell lines." (PMID 36497214, 2022). "Suppression of POLR3G activates the expression of FOXA1 and androgen receptor, two key factors that are characteristic of luminal and molecular apocrine breast cancers in which they contribute to controlling hormone response and can be targeted for therapies." (PMID 36497214, 2022). "POLR3G showed globally low expression levels but was specifically overexpressed in triple-negative (ER-, PR-, HER2-) and more occasionally in luminal B breast cancer." (PMID 36497214, 2022). "Our data support that, in the case of TNBC, suppression of POLR3G redirects, at least in parts, the gene expression signature of TNBC toward the one that was described for molecular apocrine breast cancer." (PMID 36497214, 2022). "Functional knockout of POLR3G in MDA-MB-231, a TNBC cell line frequently classified as a basal-like breast cancer subtype, reduces anchorage-independent growth and invasive capacities in vitro." (PMID 36710885, 2022). "Taken together, POLR3G/RPC32α knockout cell lines showed strongly reduced tumor and metastasis development compared to the MDA-MB-231 cell line, but POLR3G suppression did not change the expression of several principal basal breast cancer marker proteins." (PMID 36497214, 2022). "Here, we demonstrate that POLR3G is specifically overexpressed in clinical samples of triple-negative breast cancer (TNBC) but not in other molecular subtypes of breast cancer." (PMID 36497214, 2022). "Here, we show that POLR3G is the only component of the Pol III transcription apparatus that is significantly overexpressed in triple-negative breast cancer (TNBC) but not in other types of breast cancer." (PMID 36497214, 2022). "POLR3G is a critical driver of stemness and is significantly overexpressed in TNBC but not in other breast cancers." (PMID 38600165, 2024). "Deletion of POLR3G, the specifying subunit of the embryonic isoform of Pol III in a TNBC cell line resulted in reduced tumor growth, suppressed metastasis, and induced expression of transcription factors not present in TNBC but characteristic of other types of breast cancer." (PMID 36497214, 2022).
transitional cell carcinoma (4 papers, 2020 to 2025). A malignant neoplasm arising from the transitional epithelium, usually affecting the urinary bladder, ureter, or renal pelvis. "However, POLR3G was also identified in clinical data as one out of five genes in a risk signature predicting the prognosis of patients with hepatocellular carcinoma, significantly upregulated in transitional cell carcinoma, and increased POLR3G expression was detected in prostate tumor biopsies." (PMID 36497214, 2022). "Additionally, a correlation has been observed between the overexpression of POLR3G and unfavorable prognostic outcomes in transitional cell carcinoma." (PMID 38240703, 2024). "However, the role of POLR3G in transitional cell carcinoma (TCC) has not been reported." (PMID 33194434, 2020).